EZH2 (enhancer of zeste 2 polycomb repressive complex 2 subunit)
Diseases named in the same sentence as EZH2 in open-access papers (continued):
Sharing a sentence is not in itself a finding about the gene and the disease.
cancer (continued). "Overexpression of EZH2 is associated with more clinically aggressive cancers, resulting in poor prognosis; however, due to molecularly and clinically distinctions among cancers, the exact role of EZH2 and possible interaction with HPV remains elusive." (PMID 41614754, 2025). "In cancer, alterations of EZH2 include gain- or loss-of-function gene mutations, overexpression of the EZH2 protein, and mutations of the H3K27 demethylase gene UTX or the SWI/SNF (INI1, SMARCA4, or SMARCA2) chromatin-remodeling complex." (PMID 39941804, 2025). "A similar negative correlation between H3K27me3 and H3K27ac was reported in stem cells with EZH2 knock-out, or cancer cells expressing the H3-K27M mutation, in which loss of H3K27me3 led to elevated histone acetylations." (PMID 40504770, 2025). "Among the alterations that affect the expression and catalytic function of EZH2 in cancer, translocations, gene amplifications, mutations in functional domains and alternative transcripts have been described." (PMID 41153744, 2025). "Our work summarizes the structure of EZH2, explains the mechanisms underlying its elevated expression in cancer, and delineates its role in cancer progression." (PMID 40028035, 2025). "Overexpression or (gain-of-function) mutations of EZH2 have been detected in several cancers, indicating the oncogenic role of EZH2." (PMID 40284428, 2025). "At this level, cancer initiation interrelates with mutations impairing the action of enhancer of zeste homolog 2 (EZH2), which participates in H3K27 methylation and is a part of polycomb repressive complex 2 (PRC2)." (PMID 40361492, 2025). "For instance, cancer cells with ARID1A mutations become highly dependent on the activity of enhancer of zeste homolog 2 (EZH2), a core component of the opposing PRC2 complex." (PMID 40940815, 2025). "The suppression of epigenetic gene expression resulting from the overexpression of EZH2 is associated with poor prognosis in various cancers." (PMID 40308579, 2025). "EZH2 overexpression was found to be associated with heightened aggressiveness of cancer and the advanced disease state of solid tumors in a wide range of different cancer types, including prostate, breast, bladder, and endometrial cancers." (PMID 39500892, 2024). "Conversely, Wnt/β-Catenin has been implicated in the build-up of β-Catenin and EZH2 within cisplatin-resistant and cancer stem cell (CSC) populations." (PMID 38600608, 2024). "Signaling cascade molecules, including pERK, pSTAT3, and MYC have all been implicated in promoting EZH2 transcriptional activation in different cancers." (PMID 38339397, 2024). "EZH2 has been extensively studied in the context of cancer, where it is often overexpressed and associated with a worse prognosis." (PMID 39120328, 2024). "The diverse roles of EZH2 in various biological processes contribute to its association with numerous diseases, notably cancer." (PMID 38534385, 2024). "Overexpression of EZH2 has been observed in many types of cancer and is often associated with poor prognosis." (PMID 39014263, 2024). "Current drugs have been developed to target core subunits of PRC2 and PRC1, such as EZH2, and understanding the specific roles of individual complex variants in particular cancer types is pivotal." (PMID 38600608, 2024). "Previous studies have shown that EZH2 increases lipid synthesis in a variety of cancers and is associated with poor prognosis." (PMID 39703843, 2024). "The pathological role of EZH2 is highlighted by over-expression or gain-of-function mutations in various cancers." (PMID 38346162, 2024). "Second, pharmacological EZH2 inhibition by DZNep is associated with beneficial therapeutic effects in several cancers." (PMID 39524044, 2024). "ARID1A, a member of the SWI/SNF family can interact with EZH2 to inhibit IFN-responsive gene expression in cancer cells whose mutations can shape the cancer immune phenotype and immunotherapy." (PMID 38461299, 2024).
cancer (continued). "Previous data in multiple studies have indicated that high EZH2-expression is linked with oncogenic activity in various cancer entities." (PMID 40135141, 2024). "Increasing evidence suggests that the dysregulation of EZH2 expression in various cancers is closely associated with tumorigenesis." (PMID 39655332, 2024). "Prior reports indicate associations between EZH2 and cancer initiation, progression, metastasis, metabolism, drug resistance, and immune regulation." (PMID 38612589, 2024). "For example, inhibitors of the PML-NB-associated H3K27me3 ‘writer’ EZH2, which were originally developed for the treatment of various cancers, have been found to suppress HSV, HCMV, and AdV gene expression and lytic replication in cell culture." (PMID 38399958, 2024). "Similar to the dual role of EZH2 in cancer pathogenesis, existing research indicates that the loss of EZH2 can also lead to drug resistance in AML." (PMID 39655332, 2024). "Mutations in EZH2 found across various cancer types have prompted efforts to target it therapeutically in cancers characterised by epigenetic dysregulation." (PMID 39682746, 2024). "A study of nearly 700 archival patient tissue samples, encompassing different cancer types including CM and cancers of the endometrium, prostate, and breast, revealed a significant association between EZH2 expression and high proliferation rate." (PMID 39518098, 2024). "The ERK, MYC, and STAT3 signaling pathways have all been implicated in the activation of EZH2 in different types of cancer, including hematopoietic malignancies." (PMID 38339397, 2024). "Supporting this, analysis of the Cancer Genome Atlas database reveals a close association between EZH2 and SKP2 expression in human malignancies." (PMID 38862595, 2024). "High-risk HCMV strains, like other oncoviruses, induced EZH2 and Myc expression, potentially contributing to the development and progression of cancer." (PMID 38534385, 2024). "In alignment with previous research, our study provides a foundation for understanding and determining EZH2-expression in high-risk carcinomas." (PMID 40135141, 2024). "FHL1 can be silenced by miR-410 or EZH2 epigenetically and regulates cancer cell growth, and is associated with transcriptional machinery." (PMID 36752296, 2023). "When EZH2 is mutated or aberrantly expressed, it usually indicates the development and progression of cancers." (PMID 36545914, 2023). "The association between EZH2 and cancer-infiltrating immunocytes was studied through TIMER and TISIDB." (PMID 37069494, 2023). "SMARCB1 mutated cells were found to be dependent on EZH2, a component of PRC2, and EZH2 inhibitors were tested with SMARCB1 mutated cancer patients in clinical trials." (PMID 37438850, 2023). "KAT2B-related acetylation of EZH2 blocks its ability for target gene regulation, resulting in cancer progression, and is associated with poor survival." (PMID 37887281, 2023). "The key roles of EZH2 in stem cell selfrenewal and the oncogenic effects EZH2 mutations and overexpression have rendered this protein attractive as a drug target for cancer therapy." (PMID 37572850, 2023). "The results showed that TOP2A was the gene most closely associated with EZH2 in various cancer types, including HCC." (PMID 38008711, 2023). "The mRNA expression data from TCGA and GEO database shows that EZH2 is upregulated in BC tissues, which suggests that the EZH2 gene is significantly associated with BC cancer risk." (PMID 36733715, 2023). "DNA–protein interactions (such as those found in Myc–Max inhibitors) and protein degradation (such as that caused by EZH2 inhibitors) have been proposed as novel therapeutic means to target critical components in cancer survival pathways." (PMID 36678591, 2023).
cancer (continued). "Overexpression of EZH2 shows enhanced cell proliferation and oncogenic capacity that is usually associated with advanced stages of human cancer progression and poor prognosis." (PMID 35841331, 2023). "Aberrant EZH2 expression is a hallmark of many cancers and elevated expression in the context of malignancy can be a marker of poor prognosis and advanced disease." (PMID 37205197, 2023). "EZH2 expression declines with age, and its loss has been linked to age-related diseases such as cancer and neurodegenerative disorders." (PMID 37445833, 2023). "This suggests that disturbances in feedback loop regulation between EZH2 and its regulatory miRNAs can confer a selective growth advantage to cancer cells and turn on genes associated with increased tumorigenicity in MB." (PMID 37345170, 2023). "The regulation of polycomb proteins (PcG), which have the ability to epigenetically silence genes, polycomb group RING finger protein 4 (BMI1) and Enhancer of zeste homolog 2 (EZH2), and the associated cancer progression are potential therapeutic targets." (PMID 38201494, 2023). "Although these drugs are not recognized as treatment options for NDDs, the similarity of EZH1 GOF variants with those found in EZH2 associated cancers suggest a potential route for epigenetic recovery of EZH1 GOF using EZH1/2 inhibitors." (PMID 37433783, 2023). "Development of EZH2 inhibitors has been driven by enhanced EZH2 activity being implicated in many diseases, including cancer." (PMID 37048131, 2023). "In the TCGA pan-cancer cohort of 10953 patients, EZH2 mutations were detected in 290 cancer samples (2.6%), dominated by missense mutations and amplifications." (PMID 36545914, 2023). "Low-dose inhibition of EZH2 is being developed to target cancer types with EZH2 mutations as these cancers are sensitive to inhibition while WT cells are unaffected." (PMID 37516914, 2023). "Related researches have already expounded that EZH2 is implicated in cell growth, expressed highly in varieties of malignant neoplasms." (PMID 38048186, 2023). "By using histone PTM global profiling, it has been demonstrated that EZH2 inhibition induces a global change of the epigenetic signature of cancer cells and yields, concomitantly, H3K27me3 loss and H3K27ac gain." (PMID 36629431, 2023). "Among 10953 TCGA pan-cancer patients, 290 (2.6%) experienced EZH2 mutation, with amplification and missense mutation being the predominant types of EZH2 gene alteration." (PMID 36545914, 2023). "EZH2 plays cancer-promoting roles by causing the formation of heterochromatin complexes and initiating gene silencing in cancer cells." (PMID 38264522, 2023). "Some studies have shown that the mutation or overexpression of the EZH2 gene is often directly related to the progression of malignant tumors." (PMID 36672374, 2023). "EZH2, from the set (c), is a well-known marker for being associated with the development and progression of different types of cancer." (PMID 37862362, 2023). "The key histone modifications implicated in the cancer process primarily involve HDACs, HMTs like EZH2, and the Histone Reader Proteins of the BET (Bromodomain and Extra-Terminal) family." (PMID 38077327, 2023). "Mutations and overexpression of EZH2 have been linked to various cancer types, including breast cancer, prostate cancer, melanoma and bladder cancer." (PMID 38041544, 2023). "This was the first report of an enhanced non-canonical interaction between the Ezh2Y641F mutant and a non-histone protein, suggesting that perhaps this is an important aspect of the oncogenic activity of EZH2 in cancers with Y641 mutations." (PMID 37664059, 2023). "Alterations in metabolic pathways is a hallmark of cancer, and EZH2 has been shown to upregulate glycolysis via increased HIF1α expression, a known transcription factor important for activism of metabolism-related genes." (PMID 37205197, 2023).
cancer (continued). "These miRNAs can alter EZH2 activity and are associated with poor clinical outcomes and therapeutic responses in cancer patients." (PMID 37345170, 2023). "Studies demonstrated that overexpression of EZH2 in cancer is associated with epithelial-to-mesenchymal transition (EMT)." (PMID 36430394, 2022). "Using an EZH2 inhibitor reinforces the synthetic lethal strategy by upregulating PIK3IP1 in AIRID1A-mutated cancers." (PMID 36185333, 2022). "A family of SAM-competitive pyridone inhibitors of EZH2, like GSK126, EPZ-6438, and CPI-1205, have been developed to treat cancers with EZH2 gain-of-function mutations as well as other EZH2-dependent cancers." (PMID 35800061, 2022). "Deregulation of epigenetic modifier genes, such as enhancer of zeste homolog 2 (EZH2) has been causally linked to several cancers." (PMID 35395831, 2022). "In summary, we found that EZH2 was highly expressed in multiple types of human cancer (including HCC) and was associated with a poor prognosis in HCC." (PMID 35627262, 2022). "EZH2 inhibitors have recently made it to the clinic for use in some SMARCB1-deficient cancers and are being explored in a wide range of other cancers." (PMID 35323214, 2022). "Dysfunctional EZH2 is associated with the development of multiple cancer types in humans and can promote immune evasion by inhibiting intra-tumoral antigen presentation, immune cell migration, and enhancing CD4+ T regulatory cell (Treg) suppressive activity." (PMID 36532284, 2022). "Mutations, both gain-of-function and loss-of-function, in PRC2 components especially EZH2 can lead to various cancer manifestations." (PMID 35795673, 2022). "The SMARCA4 deficient cancer cells display sensitivity to suppression of the enhancer of zeste homolog 2 (EZH2)." (PMID 35200537, 2022). "Oncogenic mutations of EZH2 were also important for the regulation of cancer development, driving multiple layers changes within chromatin domains in cancer." (PMID 36578923, 2022). "Univariate and multivariate Cox regression analyses suggested that EZH2 expression and nodal metastasis status, cancer stage, gender, and age were the independent risk factors affecting LIHC patients' prognosis (all p < 0.05)." (PMID 35855852, 2022). "In this study, cancer cells can be induced to a Synergistic effect by EZH2i upon genetic ablation of NF-κB, indicating that redundant survival pathway(s)/mechanism(s) of EZH2 can compensate for the loss of NF-κB activity." (PMID 36263173, 2022). "In conclusion, miR-506-3p overexpression suppresses cell migration and invasion of OvCa by reducing EZH2 expression, suggesting the underlying mechanism for miR-506-3p to mediate cancer metastasis." (PMID 35154460, 2022). "We have shown that the nuclear p85β stabilizes EZH1 and EZH2 in cancer cells with a PIK3CA E545K mutation." (PMID 35418124, 2022). "Both AKT1 and EZH2 are associated with cancer metastasis and invasion, resulting in the deterioration of tumors." (PMID 35743172, 2022). "Gain-of-function (GoF) mutations of EZH2 have been reported in B-cell lymphoma, melanoma and other cancers." (PMID 35169119, 2022). "EZH2, a histone methyl transferase subunit of a polycomb repressor complex, is associated with inflammatory diseases and numerous cancers." (PMID 36389690, 2022). "Therapeutic approaches have been suggested for the treatment of BAP1-deficient cancers such as the epigenetic drugs that inhibit EZH2, ther platinum-based compounds and PARP-1 inhibitors." (PMID 36318367, 2022). "In comparison, Y641F/N/S/H and A677G cancer mutations of EZH2 found in human B-cell lymphomas cause hypertrimethylation of H3K27 in a heterozygous genetic background by directly remodeling the active site and changing product specificity." (PMID 36351927, 2022). "Recently, several studies have shown that EZH2 is aberrantly upregulated in various malignant tumors, such as prostate and breast cancer, and is associated with advanced stages and poor prognosis." (PMID 35208478, 2022).
cancer (continued). "EZH2 mutations have also been observed in some cancers, such as B- and T-cell lymphoproliferative disorders." (PMID 36359771, 2022). "EZH2 is negatively associated with major histocompatibility complex (MHC) class I expression in different types of cancer." (PMID 36135315, 2022). "EZH2 catalyzes H3K27me3 marks to function as a master regulator in a variety of cellular processes, including cancer, and its role in cancer is linked with high proliferation rates, metastasis and poor overall survival." (PMID 35747820, 2022). "In this context, studies revealed that the downregulation of EZH2 expression in cancer is associated with an increase of apoptosis and a cell cycle arrest in the G0/G phases." (PMID 36430394, 2022). "Dysregulation of EZH2 as a histone modifier causes proliferation of cancer cells and promotes their survival and metastasis, resulting in invasion and progression of a malignant tumor." (PMID 35408658, 2022). "There is strong evidence that mutations of splicing components SRSF2 and SF3B1 cause cancer in part by enhancing the inclusion of pseudoexons with in-frame stop codons for two genes EZH2 and BRD9, respectively." (PMID 35188075, 2022). "Several specific epigenetic-targeted agents for modifiers with gain-of-function (GOF) mutations have already been approved for clinical cancer treatment, such as EZH2 inhibitors." (PMID 36120308, 2022). "We identified examples of germline SNPs near ieGenes that are associated with progression-free survival (LPP and EZH2), demonstrating the potential importance of germline SNPs acting through gene expression in cancer patient outcome post diagnosis." (PMID 35725412, 2022). "EZH2 is overactive in various cancer cells through functionally acquired mutations and overexpression." (PMID 36313363, 2022). "Aberrant EZH2 expression and signaling has been implicated in the pathogenesis of various cancers, which led to the development of the EZH2 inhibitor, tazemetostat." (PMID 36172151, 2022). "This direct m6A-dependent stabilization of EZH2 mRNA by IGF2BP1 further underlines its oncogenic role in cancer, which so far has mainly been attributed to its inhibitory action on miRNA/RISC-directed downregulation of antiproliferative target mRNAs." (PMID 35565249, 2022). "Pathway analyses revealed that EZH2-rich domains regulate genes associated with processes involved in cancer such as cell adhesion molecules, transcriptional misregulation in cancer, and cellular senescence in HeLa-S3." (PMID 36172073, 2022). "Mutation or overexpression of EZH2 occurs in multiple types of cancers, and current literature supports EZH2 as a key regulator of cancer development and a promising target for cancer therapy." (PMID 36555314, 2022). "In contrast, it was recently found that loss of EZH2 can negatively affect chemotherapeutic response in BRCA-deficient cancers." (PMID 36568963, 2022). "EZH2 was found to be upregulated in SMARCB1-deficient cancers, leading to trimethylation of lysine 27 of histone H3 (H3K27); as a result, histone and DNA were tightly bound and polycomb target genes were also broadly repressed." (PMID 35806102, 2022). "In the past decade, targeting of EZH2 in SWI/SNF-deficient cancers has been the focus of many studies." (PMID 35326450, 2022). "Previous studies have established that overexpression of EZH2 is associated with a poor prognosis in various types of cancer." (PMID 35656182, 2022). "Based on the TCGA data, EZH2 expression was associated with the prognoses for various cancers, and this was most significant for HCC." (PMID 35208478, 2022). "EZH2, as a histone methyltransferase, has been associated with cancer development and metastasis possibly through the regulation of microRNAs and cellular pathways such as EMT." (PMID 36316365, 2022). "The inhibition of EZH2 alone has previously been linked to reducing the expression of multiple genes associated with DDR pathways in multiple cancers including prostate and ovarian." (PMID 35326684, 2022).